ZEB2 (zinc finger E-box binding homeobox 2)
Diseases named in the same sentence as ZEB2 in open-access papers (continued):
Sharing a sentence is not in itself a finding about the gene and the disease.
breast carcinoma (continued). "Expression of ZEB2 was significantly reduced (mRNA by 41.5% and protein by 48.0%) in FOXP3 + BT549 cells, compared with GFP + BT549 cells, indicating that the endogenous ZEB2 gene is regulated by FOXP3 in breast cancer cells." (PMID 29963231, 2018). "Here we show by overexpression of FOXP3 and/ or miR-155 that in aggressive breast cancer lines ZEB2 is regulated independently of ZEB1, both transcriptionally, by FOXP3 and post-transcriptionally by miR-155." (PMID 29963231, 2018). "In contrast, the expression of ZEB2 was generally low in breast cancer cells compared to THP‐1 cells, an acute myelogenous leukemia cell line with known ZEB2 function, and showed weaker correlation with IL6 and IL8 expression than that of ZEB1." (PMID 28618162, 2017). "In contrast, lower levels of ZEB2 (another EMT marker) were detected in the M13SV1-EGFP-Neo cells compared to the HS578T-Hyg breast cancer cells." (PMID 28768501, 2017). "Our findings indicated that ZEB1 and partly ZEB2 regulated the characteristic inflammatory phenotype of breast cancer cells, in part through IL‐6 and IL‐8." (PMID 28618162, 2017). "ZEB2 is expressed in various human tumours, including liver cancer, colorectal cancer and breast cancer." (PMID 29115924, 2017). "Many transcriptional repressors, such as Snail, Slug, Twist, ZEB1, ZEB2, have been implicated in the regulation of EMT for a variety of cancers, including breast cancer, colon cancer, liver and HNSCC." (PMID 25749385, 2015). "In breast cancer samples, these intronic transcripts and ZEB2 are down-regulated in epithelial cells." (PMID 25798919, 2015). "Together, these results reveal that two alternatively spliced 5′UTR isoforms of the ZEB2 gene can be expressed in breast cancer cell lines and breast cancer tissues, indicating that the two promoters, driving the respective transcripts, are functional." (PMID 25762639, 2015). "We showed that transcripts from both promoters were expressed in breast cancer tissues, indicating that both promoters are targets for regulation of ZEB2 expression in breast cancer." (PMID 25762639, 2015). "To confirm that the ZEB2 region was misregulated in breast cancer epithelial cells, we examined the expression pattern of the ZEB2 protein using immunohistochemistry." (PMID 25798919, 2015). "We show that two ZEB2 transcripts derived from distinct promoters are both expressed in breast cancer cell lines and breast tumor samples." (PMID 25762639, 2015). "The transcriptional factors, ZEB1 and ZEB2 were previously demonstrated to be regulated by miR-200c, and they were found to be reciprocally expressed in breast cancer." (PMID 25329395, 2014). "In summary, the current study demonstrated that overexpression of S100A16 gene promoted EMT via Notch1/ZEB1, ZEB2/EMT pathway in breast cancer cells." (PMID 25287362, 2014). "Recent studies have shown that ZEB1 and ZEB2 are direct targets of the miR-200 family in human breast cancer cells (MDA-MB-231), canine kidney cells (MDCK), murine models, and a NCI-60 panel of cell lines." (PMID 25367080, 2014). "For example, overexpression of miR-200b and miR-200c caused MET in mesenchymal breast cancer cell lines MDA-MB-231 and BT549 by repressing ZEB1 and ZEB2." (PMID 23626803, 2013). "Of note, endogenous expression of the Zeb1, Zeb2 and Twist2 EMT inducers was also induced, further supporting the association of the EMT interactome with the claudin-low breast cancer subtype." (PMID 22654675, 2012). "MDA-MB-231 cells are metastatic breast cancer cells that express multiple zinc finger transcriptional repressors, including Snai1, Snai2, Zeb1 and Zeb2, all of which can bind Eboxes in the E-cadherin promoter and regulate EMT." (PMID 22393397, 2012). "Expression of miR-200, which promotes a mesenchymal to epithelial cell transition (MET) by inhibiting Zeb2 expression, unexpectedly enhances macroscopic metastases in mouse breast cancer cell lines." (PMID 19787069, 2009).
breast carcinoma (continued). "We have previously reported that Ets transcription factors activated by ERK pathways promote transcription of ZEB1 and ZEB2 in breast cancer cells, though it is unlikely that overexpression of ZEB1 would activate ERK pathway, due to drastic reduction of cell proliferation." (PMID 39362647, 2024). "Indeed, the HS578T-Hyg ZEB1-KO cells revealed a markedly higher ZEB2 expression than the HS578T-Hyg breast cancer cells." (PMID 38139138, 2023). "Furthermore, a targeted binding site between miR-653 and zinc finger E-box binding homeobox 2 (ZEB2) has also been validated, and hsa-circ-0004771 is reported to modulate the miR-653/ZEB2 axis to promote breast cancer progression." (PMID 37845688, 2023). "Additionally, the inhibition of ZEB2 by miR-145 allows for the expression of E-cadherin, which is known to inhibit cell migration in breast cancer." (PMID 36835085, 2023). "Further analysis of the novel ZEB1 heterodimer complex with ZEB2 may open a pathway to elucidate the uncovered functions of ZEB1 in breast cancer progression." (PMID 36910659, 2023). "Overexpression of ACSL4 contributes to ZEB2-mediated breast cancer invasion." (PMID 38078907, 2023). "Therefore, the FRA-1-miR-221/222-TRPS1-ZEB2 axis further reinforces the regulatory links between Fra-1 and ZEB2 in breast cancer." (PMID 37176013, 2023). "Similarly, the NuRD complex can also recruited by ZEB2, thus regulating the metastasis of breast cancer and the differentiation of neural cells." (PMID 35601657, 2022). "It has been shown that ZEB2 is a target of miR-625 in breast cancer." (PMID 35992812, 2022). "Atropine may bind to EMT-signaling molecules such as E-cad and ZEB-2 or inhibit the breast cancer cells receptors and thus reduce the resistance to drugs and breast cancer metastatic development." (PMID 36077256, 2022). "As an EMT regulator, ZEB2 medicated the metastasis of breast cancer." (PMID 34551777, 2021). "It will be interesting to see whether miR-203 can also attenuate the expression of Zeb2 and potentially Zeb1 in metastatic breast cancer cell models." (PMID 33414456, 2021). "Accordingly, the expression of transcriptional repressors of E-Cadherin, including zinc finger E-box-binding homeobox 1 (ZEB1), zinc finger E-box-binding homeobox 2 (ZEB2), twist-related protein (Twist), zinc finger protein, Snail, and Slug, is associated with poor prognosis in breast carcinoma." (PMID 33626096, 2021). "Indeed, loss of CdGAP in ErbB2-expressing mouse mammary tumor cells and in human breast cancer MDA-MB-231 cells resulted in a decrease of SNAIL1 and ZEB2 concomitantly with an increase of E-cadherin and reinstatement of cellular adherens junctions." (PMID 34493786, 2021). "ZEB2 is a widely known oncogene in various cancers, including lung cancer, breast cancer and OS." (PMID 32424109, 2020). "Being a direct target, an inverse association of ZEB2 with miR-200b-3p was observed in the whole breast cancer patients without stratification into IBC and non-IBC." (PMID 32708601, 2020). "Interestingly, a significant inverse correlation was observed between miR-653 and hsa_circ_0004771 or ZEB2 expression in breast cancer tumor tissues." (PMID 30979827, 2019). "In breast cancer, a proclivity to poor overall survival has been reported in ZEB2-positive cases." (PMID 30645591, 2019). "Furthermore, Kaplan–Meier survival curve analysis revealed that high expression of ZEB2 was closely related with poor prognosis in patients with breast cancer." (PMID 30979827, 2019). "Furthermore, we observed downregulation of ZEB2, a transcription factor important for the maintenance of self-renewal in canine mammary cancer cells expression." (PMID 31758045, 2019).
breast carcinoma (continued). "In addition, we observed downregulation of ZEB2, a transcription factor important for the maintenance of self-renewal in canine mammary cancer cells." (PMID 31758045, 2019). "Likewise, miR-340 and Zeb1 display a feed-forward loop involved in breast cancer progression, and miR-145 and Zeb2 leading to prostate cancer." (PMID 29843425, 2018). "Moreover, CdGAP is an essential component in the synergistic interaction between TGFβ and ErbB-2 signaling pathways during breast cancer cell migration and invasion, and is a novel E-cadherin transcriptional co-repressor with Zeb2 in breast cancer." (PMID 29545927, 2018). "Cells with high ZEB1 (and ZEB2) expression classified as basal‐B breast cancer cells." (PMID 29744893, 2018). "Interestingly, most breast cancer subtypes expressed a high level of ZEB2 and low level of RAB25, except in claudin-low subtype in which RAB25 has been described as a tumor suppressor." (PMID 30445998, 2018). "However, to confirm that changes in Vimentin and E-cadherin expression were via direct regulation by ZEB2 and not by direct interactions with FOXP3 or miR-155, we then depleted the breast cancer cells of ZEB1 or ZEB2 using siRNAs." (PMID 29963231, 2018). "We have recently uncovered a previously unknown nuclear function for CdGAP where it cooperates in a GAP-independent manner with the transcriptional repressor Zeb2 to regulate the repression of E-cadherin expression in breast cancer cells." (PMID 29545927, 2018). "Our in vitro data and in silico predictions led us to speculate that miR-155 and FOXP3 may down regulate endogenous ZEB2 in normal breast epithelia as part of epithelial homeostasis, and this is defective in breast cancer." (PMID 29963231, 2018). "We suggest that FOXP3 may help maintain normal breast epithelial characteristics through regulation of ZEB2, and loss of FOXP3 in breast cancer cells results in deregulation of ZEB2." (PMID 29963231, 2018). "In conclusion, ZEB1 and ZEB2, through the induction of various cytokines, including IL‐6 and IL‐8, facilitate tumor growth both in autocrine and in paracrine manners in basal‐type breast cancer cells." (PMID 28618162, 2017). "Furthermore, the expression profiles of ZEB1 and ZEB2 are inversely correlated with those of ESRPs in human breast cancer cell lines and tumor specimens." (PMID 28618162, 2017). "In contrast, the miR-200 family members have been shown to enhance the migration ability of breast cancer cells and to promote the metastatic colonization of breast cancer cells through up-regulating the expression of E-cadherin and down-regulating that of ZEB2 and Sec23a." (PMID 27484639, 2016). "The Foxa2, Msx2, and Zeb2 transcription factors are known to play a role in the epithelial-to-mesenchymal transition and Reln is known to be epigenetically regulated and correlates with prognostic factors in human breast cancer." (PMID 27711132, 2016). "Indeed, we observed that expression of ZEB2 is also repressed by SK228 treatment of breast cancer cells." (PMID 24967704, 2014). "Since miR-205 directly targets ZEB1 and ZEB2 in Madin Darby canine kidney cells, reduced expression of miR-205 could maintain breast cancer cells in the mesenchymal state through ZEB1/ZEB2 inhibition of E-cadherin (CDH1)." (PMID 24098490, 2013). "Expression of miR-200, which promotes a mesenchymal to epithelial cell transition (MET) by inhibiting Zeb2 expression, unexpectedly enhances macroscopic metastases in mouse breast cancer cell lines, enhances mouse breast cancer cell colonization to form distant metastases." (PMID 24026105, 2013). "The increase in vimentin expression may be due to the ~100-fold increase in ZEB2 expression, as ZEB2 is also involved in up-regulating the expression of vimentin in breast cancer cells." (PMID 19422694, 2009).
breast carcinoma (continued). "Although somewhat upregulated by individual treatments with EGF or ST, Zeb2/SIP1 was repressed in the combined treatment at all timepoints suggesting this Zeb family member is less likely to be involved in Snail1-driven breast cancer EMT." (PMID 19604397, 2009). "To determine whether miR-200 regulates Zeb2 and E-cadherin expression in these breast cancer cell lines, we transfected 4TO7 cells with mimics of miR-200b or miR-200c alone or in combination." (PMID 19787069, 2009). "Similarly, it remains unclear why shRNA-mediated knockdown of ZEB1 in the MDA-MB-231 breast cancer cells was correlated with elevated miRNA-200c-3p levels although the MDA-MB-231 cells express ZEB2 too." (PMID 38139138, 2023). "Thus, ACSL4 and ZEB2 could specifically be used as prognostic markers for breast cancer, and this axes hold promise as a new metabolic therapeutic target for highly invasive breast cancer." (PMID 38078907, 2023). "Additionally, FAT10 protein could bind and stabilise the protein zinc finger E-box-binding homeobox 2 (ZEB2) in breast cancer cells." (PMID 34571823, 2021). "However, we found this inverse association between ZEB2 and miR-200b-3p (r = −0.406, p = 0.05) when the whole cohort of breast cancer patients was combined as one group regardless of IBC and non-IBC subtyping." (PMID 32708601, 2020). "In summary, hsa_circ_0004771/miR-653/ZEB2 regulatory feedback revealed a new molecular mechanism in the pathogenesis of breast cancer, which might provide novel therapeutic targets for the treatment of breast cancer." (PMID 30979827, 2019). "Therefore, MALAT1 regulated the miR-204/ZEB2 axis in breast cancer." (PMID 31214490, 2019). "Thus, FOXP3 and miR-155 expression are high in normal human breast epithelial cells (HMEC) where ZEB2 expression is low and conversely, where ZEB2 expression is high in the human breast cancer cell lines (BT549 and MDA-MB-231), FOXP3 and miR155 expression are low." (PMID 29963231, 2018). "Transcription factor ZEB2 activates ACSL4 expression by directly binding to the ACSL4 promoter, thereby promoting cellular lipid storage and fatty acid oxidation to drive breast cancer metastasis." (PMID 40050614, 2025). "MiR-200c is a critical regulator in the metastatic progression of various cancers, particularly breast cancer, by modulating ZEB1 and ZEB2, which in turn influence the EMT process." (PMID 39859424, 2025). "Among various types of cancers, human breast cancer cells and human HNSCC cells have been well characterized in EMT studies, and show a positive correlation between the expression of ZEB1/2 (ZEB1 and ZEB2) and aggressive cancer cell phenotypes." (PMID 39362647, 2024). "The protein complex GATA3/G9A/MTA3 represses ZEB2, and other genes involved in EMT, leading to suppression of metastasis from human breast cancer cells in mice." (PMID 39242600, 2024). "FOXA2 recruits the transcriptional repressor TLE3 to the ZEB2 promoter and inhibits the expression of the EMT-related transcription factor ZEB2, thus preventing EMT in breast cancer cells." (PMID 38605023, 2024). "In two breast cancer studies, the linc-ROR acted as a miR-205 sponge to overexpress ZEB1 and ZEB2 and decrease the expression of E-cadherin." (PMID 36827545, 2023). "As expected, overexpression of ACSL4 significantly restored the invasive and metastatic capacities of ZEB2 knockdown cells by 35.1% and 32.4%, respectively, indicating that ACSL4 is essential for ZEB2-mediated breast cancer invasion and migration." (PMID 38078907, 2023). "In the TCGA dataset, we assessed the expression of key epithelial marker E-cadherin (CDH1) and mesenchymal markers, including vimentin (VIM), MMP9, SNAI2, ZEB1, and ZEB2, about VISTA expression in breast cancer patients using Spearman correlation analysis." (PMID 37152039, 2023).
breast carcinoma (continued). "AP‐1 has been shown to directly bind with the promoter of Snail and ZEB2, thus activating their transcription, leading to EMT and metastasis of skin cancer, cervical cancer, and breast cancer." (PMID 35601657, 2022). "Another study found that TLE3, a transcription corepressor recruited by FOXA2 to the ZEB2 promoter, inhibits the expression of the EMT-related transcription factor ZEB2, thereby suppressing the EMT of breast cancer cells." (PMID 36451774, 2022). "The high expression of ROR attenuates the inhibition of miR-205 on ZEB2 and promotes the expression of ZEB2, which can induce epithelial mesenchymal transformation (EMT) and metastasis of breast cancer." (PMID 35152838, 2022). "Significant downregulation of the miR-200 family, which consists of miR-141, miR-200a, miR-200b, miR-200c, and miR-429, regulates the expressions of mesenchymal markers ZEB1, ZEB2, TWIST1, TWIST2, Snai1, and Snai2 and promotes EMT in breast cancer." (PMID 37533517, 2022). "The model implemented by SPINNAKER predicted a total of 99,662 sponge interactions, with 4223 associated to breast cancer and 2 of them experimentally confirmed in breast cancer (CNOT6L-PTEN and ZEB2-PTEN)." (PMID 35524174, 2022). "Circular RNA hsa_circ_001783 sponges miR-200c-3p in breast cancer, which leads to the upregulation of miR-200c-3p target genes ZEB1, ZEB2, and ETS1." (PMID 34439151, 2021). "MYC increases breast cancer stem cell-like properties and EMT by binding to DOT1L and p300, which stimulates SNAIL, ZEB1, ZEB2 transcription and promotes lysine-79 methylation and H3 acetylation through gene epigenetic modification." (PMID 33390842, 2021). "With the expression of ZEB2, FAT10 protein induces the pro-metastasis effect in breast cancer tissues." (PMID 34571823, 2021). "In breast cancer, it was found that FOXP3 and miR-155 work together to down regulate ZEB2, resulting in reduced invasion." (PMID 33800594, 2021). "The negative correlation between hsa_circ_001783 and miR-200c-3p and positive correlation between hsa_circ_001783 and ZEB1, ZEB2, and ETS1 were further observed in the tumor tissues from breast cancer patients." (PMID 30670688, 2019). "FAT10 directly bonded to the DNA-binding transcriptional repressor zinc finger E-box-binding homeobox 2 (ZEB2) and decreased its ubiquitination in breast cancer cells, thereby enhancing its pro-metastasic effect." (PMID 31067743, 2019). "The transcription factor ZEB2 has been predicted to be a transcriptional repressor of the CDH1 in human glioblastomas, breast cancer and renal cell carcinomas." (PMID 30645591, 2019). "After removing ZEB2 from consideration, ZEB1 was most significantly correlated with stromal infiltration in breast cancer (r2 = 0.65, p = 3.99 × 10−180)." (PMID 31780722, 2019). "Specifically, linc-ROR overexpression prevents the degradation of mir-205 target genes in breast cancer cells, including the EMT inducer ZEB2." (PMID 31214490, 2019). "Previous reports proved that miR-203 possesses a tumor suppressive role in many cancers, including lung cancer, GC, breast cancer, HCC, and colorectal cancer, and miR-203 regulates a cohort of metastatic genes including ZEB2 in prostatic carcinoma." (PMID 30464170, 2018). "Basal‐A and luminal epithelial breast cancer cells expressed low or undetectable levels of ZEB1 (and ZEB2)." (PMID 29744893, 2018). "This gives a new insight into the role of ZEB2 and also perhaps of ZEB1 in breast cancer metastasis." (PMID 29963231, 2018). "We conclude that down regulation of ZEB2 by miR-155 and FOXP3 alters the migratory and invasive potential of breast cancer cells." (PMID 29963231, 2018). "Previous reports indicated that the upregulation of ZEB1 by TGF-β or other cytokines/growth factors is accompanied by ZEB2 upregulation, and that both ZEB1 and ZEB2 are highly expressed in breast cancer cells with aggressive phenotypes." (PMID 29969465, 2018).